STPG3 (sperm-tail PG-rich repeat containing 3)
Synonyms: C9orf173; FLJ40246
Tractability: No criterion of Open Targets' tractability assessment is met for any kind of drug.
Gene: Protein-coding gene on chromosome 9 (137,250,608 to 137,253,483, forward strand). Ensembl gene ENSG00000197768.
Subcellular location (Human Protein Atlas): Vesicles
Gene Ontology:
Cellular component: cytoskeleton
Genetic constraint (gnomAD): Loss-of-function variants: 40 observed, 32.1 expected, observed/expected ratio (o/e) 1.25, 90% interval 0.97 to 1.62. The synonymous counts are far from expectation, so gnomAD's model fits this gene poorly and the ratio says little. Missense variants: 507 observed, 371.84 expected, observed/expected ratio (o/e) 1.36, 90% interval 1.27 to 1.47. Synonymous variants: 209 observed, 154.66 expected, observed/expected ratio (o/e) 1.35, 90% interval 1.21 to 1.52.
Homologues: Orthologues: chimpanzee STPG3 (98% identical), macaque STPG3 (82% identical), dog STPG3 (66% identical), rat Stpg3 (65% identical), mouse Stpg3 (64% identical), pig STPG3 (59% identical), guinea pig STPG3 (56% identical).
Diseases named in the same sentence as STPG3 in open-access papers:
STPG3 is named in the same sentence as 1 disease in open-access papers, as found by Europe PMC text mining. Sharing a sentence is not in itself a finding about the gene and the disease.
STPG3 shares sentences with these, for which no sentence is quoted: cardiovascular disease (1 paper).